IL6 (interleukin 6)
Diseases named in the same sentence as IL6 in open-access papers (continued):
Sharing a sentence is not in itself a finding about the gene and the disease.
COVID-19 (continued). "Interestingly, a significant correlation between the critical illness/intensive care unit (ICU) admission of COVID-19 patients and serum levels of IL-6 and TNF-α has been documented." (PMID 35456120, 2022). "A previous systematic review defied the role of IL-6 in COVID-19." (PMID 35407485, 2022). "Patients with severe COVID-19 typically have increased serum levels of IL-6, IL-8/CXCL8, CXCL9, CXCL10, TNF-α, MCP1/CCL2, RANTES/CCL5, IL-18, and MIP-1α/CCL3, which promote a sustained pro-inflammatory state that may persist for up to 60 days." (PMID 36289507, 2022). "Doxycycline (a tetracycline) reduces IL-6, IL-1β and TNF-α levels, however, doxycycline treatment did not have a significant clinical impact on time to recovery, hospital admissions or deaths related to COVID-19 in patients with high risk to adverse outcomes." (PMID 35720378, 2022). "During severe COVID-19, the cytokine storm is characterized mainly by the overexpression of IL-6." (PMID 35062298, 2022). "Females' have lower production of pro-inflammatory interleukin-6 (IL-6) following viral infection that could explain the development of COVID-19 symptoms." (PMID 35820935, 2022). "At the same time, IL-6 may even serve as an early biomarker for monitoring inflammatory and immune responses in COVID-19." (PMID 35883738, 2022). "This resulted in a model including CCL20, IL6, IL10, and hsa-miR-451a, which was compared to a model with only CCL20 (the most statistically significantly associated factor with fatal COVID-19, adjusted p = 1.02 × 109)." (PMID 34957382, 2022). "The proposed central role of a cytokine storm in COVID-19 disease escalation prompts the question of whether interleukin (IL)-6 normalization strategies during the maladapted inflammatory response could be useful." (PMID 35634332, 2022). "Elevations of TNF-ɑ and IL-6 are strong independent predictors of poor prognosis in COVID-19." (PMID 35832759, 2022). "IL-6 is an important inflammatory marker predicting severity of COVID-19." (PMID 36366295, 2022). "Next, we assessed the level of IL-6 in plasma and saliva of the COVID-19 patients." (PMID 36163397, 2022). "Also, IL-6 was reported to contribute to immune cell hyperactivation and target organ dysfunction in COVID-19." (PMID 35529862, 2022). "Considering the importance of IL6 in COVID-19-related pathomechanism, anti-IL6 therapies may be effective for severe COVID-19, including selective inhibitors of ADAM-17 or sgp130Fc, which inhibits IL6 signal transduction." (PMID 35165525, 2022). "Immune dysregulation and ARDS in COVID-19 appear to be most significantly influenced by IL-6." (PMID 36558489, 2022). "Interestingly, according to some studies, IL-8 showed a better correlation than serum IL-6 levels in predicting COVID-19 severity and mortality." (PMID 35743825, 2022). "Moreover, some authors have already proposed anti-IL-6 as target for the treatment of severe COVID-19 patients." (PMID 35192635, 2022). "Noteworthy, IL-10 is elevated earlier than IL-6 in COVID-19 patients." (PMID 35529862, 2022). "Increased levels of IL-6 in COVID-19 increase the free iron levels by increasing ferritin levels." (PMID 35419223, 2022). "In this study, we identified that Nsp14 increases nuclear translocation of p65 and induces the expression of NF-κB’s downstream cytokines, such as IL-6 and IL-8, which have also been detected in lung tissues of COVID-19 patients and animal models of SARS-CoV-2 infection." (PMID 36177032, 2022). "Additionally, IL-6 and CRP have been associated with COVID-19 severity, with IL-6 being the most frequently reported cytokine elevated in COVID-19 associated CS." (PMID 35500008, 2022). "Several inflammation-associated markers such as C-reactive protein (CRP), ferritin, fibrinogen, D-dimer, neutrophil levels, urea in blood, and the cytokines IL-6, IL-10, and TNF-α have being associated with COVID-19 progression and play an important role in the development of acute lung injury." (PMID 36203752, 2022).
COVID-19 (continued). "IL-6, MCP-1 and IP-10 have been found to be strongly associated with disease severity in COVID-19." (PMID 35365215, 2022). "The same is true of a meta-analysis on IL-6 antagonists and mortality in hospitalized COVID-19 patients; fungal infections were evaluated in only 5 out of 22 RCTs considered for infections, and viral reactivation was evaluated in only 1 of these 22 RCTs (20 patients)." (PMID 36289881, 2022). "The authors suggested that the level of CD3+CD4+ T cells could have a predictive value for the early detection of severe COVID-19 forms and the selection of patients requiring rapid aggressive treatment with corticosteroids or IL-6 inhibitors." (PMID 35632823, 2022). "Moreover, it is now known that patients with acute COVID-19 present increased blood levels of pro-inflammatory cytokines (e.g., IL-6, IL-8, TNFα) that drive neutrophil mobilization and are associated with poor prognosis in severe cases." (PMID 36466824, 2022). "Although it is often cumbersome to stratify and recognize the right patients to treat with anti-IL-6 agents within the right time of COVID-19 pathophysiology, some important inflammatory and respiratory parameters have been suggested to help clinicians manage the decision." (PMID 35645219, 2022). "Upregulated IL-6 in COVID-19 patients may lead to MS exacerbation, as this cytokine has consistently been linked to worsened demyelination and histopathological scores in EAE models." (PMID 35572514, 2022). "The REMAP CAP study also showed benefit of IL-6 antagonists for critically ill COVID-19 patients." (PMID 35991665, 2022). "Variables of interest, such as procalcitonin, fibrinogen and IL-6, which literature suggests to be associated to COVID-19 disease severity, were not systematically collected and were, therefore, excluded from the multivariate analysis." (PMID 35898367, 2022). "The relevance of IL-6 trans-signaling for acute COVID-19 has recently been reported." (PMID 35732153, 2022). "The early responses of elevated IL-6 expression might drive activation of T cell immunity against COVID-19." (PMID 35248063, 2022). "IL-6 is one of the main inflammatory markers involved in the critical phase of COVID-19." (PMID 36037223, 2022). "Laboratory biomarkers, such as C-reactive protein (CRP), ferritin, D-dimer, cardiac troponin (cTn), NT-proBNP, lymphopenia, neutropenia, and, if available, circulating IL-6 levels have been associated with MIS in Stages 2–3 and also with poor outcomes of COVID-19." (PMID 36430430, 2022). "IL-6 is believed to play a crucial role in the development of cytokine storms, contributing to the occurrence of ARDS and causing interstitial pneumonia in patients with severe COVID-19." (PMID 36115998, 2022). "For example, the levels of IL-6 rise sharply in severe manifestations of COVID-19." (PMID 36514048, 2022). "Alongside PAI-1, IL-6 is an independent predictor of COVID-19 severity." (PMID 35784318, 2022). "Our unpublished data showed some increased IL-6 levels in some COVID-19 patients." (PMID 35891295, 2022). "Other theories to explain the decreased amount of this cell subset in COVID-19 are the IL-6 induced transformation of regulatory T cells into Th17 effector cells and the hypoxia-induced degradation of Foxp3 through the activation of the hypoxia-inducible factor-1α." (PMID 36045688, 2022). "The reason why COVID-19 patients presented lower levels of lymphocytes is still unclear, although some hypothesis suggested that COVID-19 increases levels of tumor necrosis factor-α and interleukin-6, which are closely correlated with lymphopenia." (PMID 35806866, 2022). "IL-6 was tested in 21 patients (46.7%) as a COVID-19 outcome predictor." (PMID 36547597, 2022). "Secondly, IL-10 concentrations are elevated earlier than IL-6 in COVID-19 patients." (PMID 36123740, 2022). "An elevated CRP may reflect elevated IL-6 levels, and both of these can perpetuate the inflammatory diabetogenic process of COVID-19 as well." (PMID 36498589, 2022).
COVID-19 (continued). "TSH levels in patients hospitalized for COVID-19 were correlated with IL-6 levels in one study." (PMID 36556379, 2022). "A study that compared the responses in patients with varying severity of COVID-19 and acute dengue infection at different time-points showed significantly higher levels of IL-6, IL-10 and MIP-3α among those who developed COVID-19 pneumonia and DHF than those with mild manifestations." (PMID 35874775, 2022). "Present in high levels in the serum of COVID-19 patients, IL-6 is speculated to enhance viral entry by activating the AT1R signaling cascade." (PMID 35021853, 2022). "Indeed, hyperglycemia denied the beneficial effect of tocilizumab, a monoclonal antibody blocking the effect of IL-6, in terms of mortality reduction in COVID-19 patients." (PMID 35329890, 2022). "In the treatment of myocarditis during COVID-19, steroid therapy may yield favorable results; the use of other agents, such as IL-6 inhibitors, intravenous immune globulin, and colchicine, seems questionable." (PMID 36143039, 2022). "In addition, the distinct effects of different anti-cytokine strategies (e.g., corticosteroids, IL-1/IL-6/JAK-STAT inhibition) on eosinophils in patients with COVID-19 should be further appraised." (PMID 36557676, 2022). "The production of IL-6 by epithelial cells in COVID-19 leads to the activation of STAT3; therefore, gene variants that reduce expression may have a protective effect against SARS-Cov-2." (PMID 35327350, 2022). "IL-6 blockade or reduced induction may be a new treatment strategy for critically ill patients with COVID-19." (PMID 35843719, 2022). "However, despite a strong correlation between IL-6 levels and COVID-19 disease severity, current attempts to suppress IL-6 signaling during severe COVID-19 infection have been met with variable results." (PMID 35512020, 2022). "Furthermore, the results indicated the great importance of IL-6 in monitoring severe cases, especially COVID-19 severity cases." (PMID 36010198, 2022). "This is particularly interesting as there is now evidence to suggest that Th17, and the Th17 inducer cytokine IL-6, could be a driver of the COVID-19 cytokine storm, although mechanistic insight so far is inconclusive." (PMID 36081770, 2022). "Using an in vitro model of human hippocampal progenitor cells, we have already demonstrated that treatment with high concentrations of IL6, similar to those found in peripheral blood of COVID-19 patients (~50-500 pg/ml), can reduce neurogenesis and increase apoptosis." (PMID 36195636, 2022). "Sustained production of IL-6 in severely ill COVID-19 patients may lead to prolonged activation of B cells and stimulate them to produce antibodies that increase both in terms of number and affinity." (PMID 35256646, 2022). "Randomised controlled trials with IL-6 inhibitors in COVID-19." (PMID 35340805, 2022). "Compared to non-obese individuals, obese individuals had greater COVID-19 severity, hypoxemic respiratory failure and higher baseline initial serum levels of C-reactive protein and IL-6 (associated with low-grade-chronic inflammation)." (PMID 35957811, 2022). "Tocilizumab is an IL-6 inhibitor that has been FDA approved for chimeric antigen receptor (CAR) T cell-induced cytokine release syndrome (CRS) and has shown promise in the treatment of COVID-19 associated acute coronary syndrome." (PMID 35402051, 2022). "The expression of IL-6 and PAI-1 in COVID-19 and underlying diseases." (PMID 35784318, 2022). "In addition, to the COVID-19 patients, particularly those admitted in ICU, pathogenic Th1 cells increased rapidly along with GM-CSF and IL-6 secretion." (PMID 35464491, 2022). "Among these, IL-6 is a predictor of mortality in COVID-19 patients, which may explain why primary evidence suggests that IL-6 inhibitors have shown promise as treatments." (PMID 35850685, 2022).
COVID-19 (continued). "In particular, nonspecific immune responses at the onset of COVID-19, such as the production of cytokines like TNF-α and IL-6 from macrophages or IFN-γ from bystander T cells, and lymphopenia have been believed to be risk factors for severity and mortality of COVID-19." (PMID 36447262, 2022). "Recent research has elucidated the role of IL-6 blockade in the treatment of COVID-19." (PMID 35566412, 2022). "Thus, the reduced expression of this miRNA in severe patients is related to an increase in IL-6 production, which has been reported in severe and critical COVID-19 patients, where IL-6 acts as a vital amplifier." (PMID 35130828, 2022). "Moreover, T cell exhaustion was also observed, concomitant with the higher expression of PD-1 and increased serum IL-6 and IL-10 in patients who were infected by COVID-19." (PMID 35271463, 2022). "In COVID-19, cytokine storms are triggered by the action of IFNγ, TNFα, IL-1, IL-2, and IL-6." (PMID 34436742, 2022). "In addition, it was reported that severe COVID-19 patients have higher levels of IL-6 and its expression level is related to pulmonary inflammation and extensive lung damage." (PMID 36081604, 2022). "On the other hand, values of C-reactive protein, IL-6, and other biochemical factors such as lactate dehydrogenase, aspartate aminotransferase, and alanine aminotransferase exhibited high specificity against COVID-19." (PMID 35281265, 2022). "Previously, we highlighted an elevation of IL-6 as one of the COVID-19 characteristic features." (PMID 36430621, 2022). "In patients with COVID-19, IL-6-induced CRS has been observed." (PMID 35992697, 2022). "Other mechanisms through which Se could assist in COVID-19 management is through control of ROS-driven endothelial damage, reduced IL-6 pathway response and the stimulation of the innate immune system." (PMID 35057415, 2022). "For instance, serum levels of pro-inflammatory cytokines, such as interleukin-6 (IL-6), tumor necrosis factor-alpha (TNFα), and IL-10, are elevated in patients with COVID-19, especially in those treated in the intensive care unit, correlating positively with disease severity." (PMID 35806986, 2022). "Several studies have reported that the level of inflammatory cytokines, especially IL-6, is correlated with COVID-19 severity and could also predict the need for mechanical ventilation." (PMID 36359290, 2022). "Of relevance to COVID-19, zinc deficiency can lead to a dysfunctional immune response with reduced activity of innate immune cells, lymphopenia and activation of NF-KB signalling inducing production of IL-6 and other cytokines involved in “cytokine storm”, characteristic of COVID-19." (PMID 35057415, 2022). "Overall observed deactivation of various interleukin pathways in COVID-19 patients might be partially due to anti-IL-6 treatment (one patient) and/or potential glucocorticoid treatment (at least two COVID-19 patients received prednisolone while at the ICU)." (PMID 36526981, 2022). "IL-6 inhibitors have been evaluated in COVID-19 patients to manage systemic inflammation." (PMID 36278757, 2022). "COVID-19 symptoms rapidly become critical 7–10 days after onset, which is associated with an increase in acute-phase response markers, including CRP and ferritin, and inflammatory cytokines, including IL-6, IL-2, and TNF-α." (PMID 34436742, 2022). "In addition, it was also found that the plasma levels of IL2, IL7, IL10, IL-6, TNFα, and e lymphopenia were higher in patients with COVID-19." (PMID 35295802, 2022). "Likewise, upregulation of cytokines namely IL-6 which is a key element in multi-organ damage including kidney injury, has been frequently recorded in COVID-19 patients." (PMID 35663932, 2022). "Higher levels of inflammasome-derived products and IL-6 found in the sera of the severe COVID-19 patients indicate that these factors might be a marker of COVID-19 severity." (PMID 35281455, 2022). "IL-6 level was the most potent predictor of COVID-19 progress and severity." (PMID 36675695, 2022).
COVID-19 (continued). "Supporting this possibility are previous findings indicating that high levels of TNF-alpha and IL-6 correlate negatively with T cell numbers in severe COVID-19 in the general population, and that B cell numbers and antibodies are reduced in COVID-19 patients with hematologic malignancies." (PMID 36700209, 2022). "We observed that elevated IL-6 levels were consistently reported in several COVID-19 studies, suggesting that it might be used as a disease severity predictor." (PMID 36506506, 2022). "Early Italian observational cohort studies with IL-6 inhibitors in COVID-19." (PMID 35340805, 2022). "It was also observed that maternal selenium level also showed a correlation with D-dimer and IL-6 level in COVID-19 pregnant women, and hence, selenium status may be a preventative/predictive factor for COVID-19 severity, inflammation, and thrombosis." (PMID 35563199, 2022). "In the present study we evaluated the changes in serum IL-6, IL-10, and IL-17A levels and the cytometric lymphocyte profiles in 144 COVID-19 patients at admission and after one week of hospitalization, also in relation to steroid treatment before hospitalization." (PMID 35893398, 2022). "Additionally, a meta-analysis revealed that serum IL-6 concentration was, on average, 2.9-fold higher in complicated COVID-19, defined as the presence of ARDS, ICU admission, or severe/critical COVID-19, as compared to their non-complicated counterparts." (PMID 35572514, 2022). "Together, our finding confirmed that the rs2069837 A to G variation may play a protective role against COVID-19 by the decreasing expression of IL-6 and inhibiting an excessive cytokine storm, especially in the male." (PMID 35368020, 2022). "It was found that as a crucial cytokine, IL-6 itself could also mark the disease severity of COVID-19." (PMID 36403042, 2022). "The best test performance for differentiating bacterial/fungal secondary infections and COVID-19 and/or ECMO associated inflammation was achieved by IL-10 (ROC-AUC 0.84) and a multivariant step-wise regression model including CRP, IL-6, PCT, and IL-10 (ROC-AUC 0.93)." (PMID 36275812, 2022). "In addition, both serum IL-6 and IL-10 significantly declined after one week of hospitalization in mild and moderate COVID-19 patients." (PMID 35893398, 2022). "However, other studies have shown that some of the COVID-19 patients not only had higher levels of serum IL-6 but also the severe form of the disease was predicted by the imbalanced cytokine production." (PMID 36584119, 2022). "Determining how various immune aberrancies, including those described here and others such as elevated IL-6 or an impaired renin-angiotensin system might contribute to the pathogenesis of severe COVID-19 will require the development of new animal models." (PMID 35040666, 2022). "Increased IL-6 levels promote chronic inflammation, which is characteristic in patients with inflammatory diseases like rheumatoid arthritis, autoimmune diseases, as well as in COVID-19." (PMID 36139806, 2022). "Independent associated factors of serum IL-6 and TNF-α levels in COVID-19 patients (n = 218)." (PMID 36419783, 2022). "In patients with COVID-19, IL-6 plays a role in the cytokine storm that damages the lungs." (PMID 36111104, 2022). "Since an increase in the levels of IL-6 has been described as a consequence of the overactivation of the immune system in COVID-19 patients, the use of a blocker for such interleukin was suggested in order to limit the inflammatory process triggered by the virus." (PMID 36524015, 2022). "The relationship between interleukin-6 and COVID-19 severity has been investigated by many studies." (PMID 35204599, 2022). "In severe COVID-19 cases, activated T lymphocytes target infected body cells, causing apoptosis and necrosis until T lymphocytes are exhausted, which is related to higher levels of Th17 and CD8 T cells, as well as IL-6." (PMID 36298501, 2022).